ANKRD23 (ankyrin repeat domain 23)
Description:
May be involved in the energy metabolism. Could be a molecular link between myofibrillar stretch-induced signaling pathways and muscle gene expression.
Synonyms: DARP; FLJ32449; MARP3
Tractability: No criterion of Open Targets' tractability assessment is met for any kind of drug.
Gene: Protein-coding gene on chromosome 2 (96,824,526 to 96,857,934, reverse strand). Ensembl gene ENSG00000163126.
Subcellular location: Nucleus
Subcellular location (Human Protein Atlas): Cytosol; Nucleoplasm; Actin filaments
Gene Ontology:
Molecular function: protein binding; titin binding; transcription cis-regulatory region binding
Biological process: positive regulation of transcription by RNA polymerase II; response to mechanical stimulus
Cellular component: nucleoplasm; nucleus; I band; intercalated disc; myofibril
Genetic constraint (gnomAD): Loss-of-function variants: 54 observed, 40.5 expected, observed/expected ratio (o/e) 1.33, 90% interval 1.07 to 1.67. The upper end of that interval is the gene's LOEUF score, 1.67, which puts it in group 6 of 6, group 1 being the genes least tolerant of losing a copy. Missense variants: 416 observed, 388.71 expected, observed/expected ratio (o/e) 1.07, 90% interval 0.99 to 1.16. Synonymous variants: 167 observed, 150.41 expected, observed/expected ratio (o/e) 1.11, 90% interval 0.98 to 1.26.
Homologues: Orthologues: chimpanzee ANKRD23 (99% identical), macaque ANKRD23 (96% identical), mouse Ankrd23 (82% identical), rat Ankrd23 (82% identical), dog ANKRD23 (82% identical), pig ANKRD23 (81% identical), rabbit ANKRD23 (80% identical), guinea pig ANKRD23 (65% identical).
Diseases named in the same sentence as ANKRD23 in open-access papers:
ANKRD23 is named in the same sentence as 25 diseases in open-access papers, as found by Europe PMC text mining. Sharing a sentence is not in itself a finding about the gene and the disease. The quoted sentences say what the papers report.
type 2 diabetes (2 papers, 2011 to 2018). "Nine genes not previously reported to be associated with type 2 diabetes were significantly dysregulated in our organ donor and PPP cohorts (ANKRD23/39, ASCL2, HHATL, NSG1, PCDH20, SCTR, CD44, FAM102B and FBXO32)." (PMID 29185012, 2018).
bladder urothelial carcinoma (1 paper, 2021). "Interestingly, a homolog of Ankrd2, Ankrd23 was recently identified as a potential dual-role cancer driver gene acting as an oncogene in renal clear-cell carcinoma, and a tumor suppressor in bladder urothelial carcinoma." (PMID 33419058, 2021).
breast carcinoma (1 paper, 2012). "Five fusions (XPA-NCBP1, HARS2-ZMAT2, HSP90B1-DKFZp547P055, IL17RB-ACTR8, ANKRD23-ANKRD39) are identified to share with the fusions identified in prostate cancer but no fusions are shared with breast cancer, colorectal cancer, ovarian cancer, and lung cancer." (PMID 23251452, 2012).
prostate carcinoma (1 paper, 2012). A carcinoma that arises from epithelial cells of the prostate gland. "Five fusions (XPA-NCBP1, HARS2-ZMAT2, HSP90B1-DKFZp547P055, IL17RB-ACTR8, ANKRD23-ANKRD39) are shared between AML and prostate cancer." (PMID 23251452, 2012).
heart diseases (1 paper, 2024). "The examples of Penk, Tceal7 and Ankrd23 highlight factors with some evidence for a function in muscle differentiation or LV heart diseases, which, however, so far have not been investigated for their specific roles in right heart (patho)physiology." (PMID 39196177, 2024).
ANKRD23 also shares sentences with these, for which no sentence is quoted: tumor (5 papers); Arrhythmia (1); cancer (1); cardiac hypertrophy (1); cardiomyopathy (1); colorectal cancer (1); diabetes mellitus (1); dilated cardiomyopathies (1); Glucose intolerance (1); heart failure (1); Insulin resistance (1); lung carcinoma (1); metabolic syndrome (1); myocardial ischemia (1); Obesity (1); ovarian carcinoma (1); renal clear-cell carcinoma (1); teratoma (1); tibial muscular dystrophy (1); viral myocarditis (1).